IL5 (interleukin 5)
Diseases named in the same sentence as IL5 in open-access papers (continued):
Sharing a sentence is not in itself a finding about the gene and the disease.
tumor (continued). "Tumor-promoted Th2 polarization can suppress T cell anti-tumor response by secreting IL-4, IL-5, and IL-10; in fact, untreated or progressive BC is associated with lower levels of IFN-γ and IL-2 and higher levels of Th2 cytokines." (PMID 39682686, 2024). "Several studies have demonstrated that IL-5 and eosinophils are vital to the production of anti-tumor immune response." (PMID 38831884, 2024). "On one hand, there is now considerable evidence implicating ILC2s in the tolerogenic processes related to tumour immune evasion, and produce large amounts of IL-13, IL-5, and IL-4." (PMID 38172434, 2024). "In our case, GM‐CSF and IL‐5 in the tumor tissue were positive, and an increase in eosinophils was observed in the renal parenchyma." (PMID 38966767, 2024). "Specifically, ILC2s have been shown to co-recruit eosinophils through the production of cytokines such as IL-5 and granulocyte–macrophage colony stimulating factor (GM-CSF), thereby providing protection against primary tumor development." (PMID 38430390, 2024). "This was followed by a decrease in IL-5 in patients where a second primary occurred, which was followed by an increase in IL-5 saliva concentrations after the tumor was removed." (PMID 38473882, 2024). "Following differentiation, Th2 cells secrete IL-4, IL-5, IL-10, IL-13, and IL-17 and eventually undergo tumor growth and metastasis." (PMID 38238581, 2024). "Consistently, blocking IL‐5 pathway also contributes to tumor growth, while overexpressing IL‐5 or IL‐4 helps to predominantly improve eosinophils, macrophages infiltration to enhance tumor clearance." (PMID 37829505, 2023). "Conversely, Th2 secretion of IL-5, an integral mediator of eosinophil activation, has been demonstrated to promote eosinophil and macrophage tumor infiltration and destruction." (PMID 37766141, 2023). "In B7H4 positive tumours, a cluster consisting of IL-5, IL-4, VEGFA, M-CSF, IFN-γ, IL-Ra, IL-8, and IL-1β was chosen for further analysis." (PMID 36980202, 2023). "This has been demonstrated within mice models, as IL-5-deficient mice display decreased eosinophil concentrations within the TIM and the subsequent loss of anti-tumor immune function." (PMID 37766141, 2023). "ACM derived from OGJ patients with early-stage tumours possessed higher levels of IL-5, which can have a dichotomous role in either inhibiting or promoting Th1 immunity according to the evidenced-based literature." (PMID 36790524, 2023). "One subgroup of the cytokines is associated with tumour growth, inflammation, tumour progression and invasion (e.g. IL1, IL17, IL22), and another subgroup includes genes associated with antitumour response (e.g. IL2, IL5, IL12 and IFN family)." (PMID 36649303, 2023). "A recent study found that IL-5-activated eosinophils upregulated glycolysis, which resulted in depletion of glucose in the tumour microenvironment." (PMID 37455828, 2023). "Apart from its role in the pathogenesis of asthma, allergy, parasitic infection, and hypereosinophilic syndromes, the IL-5/eosinophil axis is reportedly correlated with both tumor suppression and progression." (PMID 37587450, 2023). "In this regard, Th2 cells facilitate tumor growth by producing pro-tumor factors such as IL-4, IL-5 and IL-13." (PMID 37773521, 2023). "Injection of recombinant IL-5 into tumor-bearing mice, led to a ~2.5-fold decrease in tumor volume in both gastrointestinal tumor models." (PMID 36376448, 2023). "The authors found out that, due to iNOS activity, the classic Th2 response was completely (IL‐4 and IL-13) or markedly (IL‐5, IL‐6, IL‐9, and IL-10) inhibited after tumor irradiation." (PMID 37347290, 2023). "Nevertheless, given their overarching effects on tumour immunity, acting upstream of the main effector type 2 cytokines IL-4, IL-5, IL-9, and IL-13 and T cells, the prospect of therapeutically targeting these cytokines is promising." (PMID 37455828, 2023).
tumor (continued). "Th2 cells play a pro-tumorigenic role by secreting IL-4, IL-5, and IL-13, which promote tumor growth and metastasis." (PMID 37324186, 2023). "The Th1 phenotype can secrete IFN-γ, IL-2, and other factors to fight tumors, but IL-4 and IL-5 secreted by the Th2 phenotype have tumor-promoting effects." (PMID 36844875, 2023). "Even though there has been little research into how ILC2s influence tumorigenesis and/or progression, ILC2s and/or their signature cytokines, such as IL-5 and IL-13, have been shown to be involved in pro- and anti-tumor immune responses." (PMID 37896962, 2023). "Mechanistically, ILC2-derived IL-5 production induces eosinophil-mediated suppression of the anti-tumor NK cell function." (PMID 37514187, 2023). "By using a mouse model of allergic inflammation, Th2 cells, one of the major sources of IL-5, were shown to be involved in tumor rejection through the activation of innate immune cells, such as macrophages and eosinophils." (PMID 37686245, 2023). "Th2 cells are a crucial component of type II immune responses by secreting a wide spectrum of cytokines such as IL-4, IL-5, IL-9 and IL-13, which affect both tumor cells and several types of immune cells." (PMID 36376448, 2023). "The serum level of IL-12 was significantly higher in the tumor-bearing mice than in the tumor-free mice; moreover, the tumor-bearing mice also displayed a trend toward higher serum levels of IFNγ, IL-5, and IL-6." (PMID 35805045, 2022). "In support of the chief role for tumor cells in some paraneoplastic syndromes, one case report found high levels of systemic IL-5 to fall following the resection of a NSCLC." (PMID 35280806, 2022). "In contrast, IL-5, IL-17A, IL-21, IL-22, and TGFβ concentrations in the tumour tissue of IL-9 knockout mice were significantly reduced compared with wild-type mice, indicating that IL-9 controls the production of Th2- and Th17-associated cytokines." (PMID 35793807, 2022). "The reduction in IL-5 (p < 0.05), IL-6 (p < 0.01), and IL-10 (p < 0.05) in the tumor and spleen of the IHS-treated ApcMin/+ mice was further confirmed through ELISAs." (PMID 36014805, 2022). "The levels of IFNγ, TNFα, IL-5, and IL-6 were significantly higher in the mice with tumors than in the tumor-free mice." (PMID 35223517, 2022). "IL-5 is a cytokine that stimulates the production of eosinophils in the bone marrow and is mostly secreted from lymphocytes, tumor cells, and eosinophils." (PMID 35707392, 2022). "The initial serum concentrations of IL-5, IL-6, IL-8, and IL-15 in the normal control group were significantly lower than those in the tumor patients, and the difference was statistically significant (P < 0.05)." (PMID 36105450, 2022). "ILC2s can suppress immune response against tumor through IL-13-mediated enhancement of MDSCs expansion, alternatively they favor anti-tumor immunity through IL-5-mediated cooperation with DCs." (PMID 36578079, 2022). "The number of eosinophils and serum level of IL-5 was significantly increased in the peripheral blood of tumor-bearing mice treated with IL-17E, which was related to the anti-tumor activity of IL-17E." (PMID 35248028, 2022). "The secreted IL-33 recruited and activated Th2 and innate lymphoid cells 2 (ILC2) in the tumor microenvironment (TME), which stimulated tumor growth by secreting pro-tumor cytokines, such as IL-4, IL-5, and IL-13." (PMID 35910636, 2022). "While Th2 cells secrete IL-4, IL-5, and IL-10 to promote polarisation of M2 macrophages, the positive interaction between the 2 cells constructs a tumour-suppressive immune microenvironment." (PMID 35591854, 2022). "Similar antitumor activity has also been described in lung ILC2s, as IL-33-activated ILC2s produce cytokines IL-5 and IL-13, recruiting eosinophils and DCs to the tumor site, respectively, which limits tumor growth and invasion." (PMID 35409105, 2022).
tumor (continued). "The tumor cells in the lesional skin of the tumor-stage shift to a Th2 phenotype, which is characterized by the production of IL-4, IL-5, IL-10, and IL-13." (PMID 36295105, 2022). "IL-5 can create a tumor-promoting immune microenvironment locally by recruiting eosinophils, thereby promoting the metastasis of tumor cells." (PMID 35664314, 2022). "IL-5 contributes to the differentiation and survival of eosinophils in the tumor microenvironment, which facilitates tumor progression." (PMID 35223517, 2022). "An additional qPCR analysis of the tumour cells showed significant increases in Il2, Ifng, Il1b, and Il18, and decreases in Il4, Il5, and Tgfb1, indicative of Th1‐dominant immune response." (PMID 35430766, 2022). "GM-CSF, IL3, CSF2, and IL5 are important regulators of inflammation and immune suppression within the tumor microenvironment." (PMID 35574409, 2022). "T cells recognize tumor antigens, activate and amplify effector T cells, and secrete cytokines such as IL-2, IL-4, IL-5, IFN-γ and granase to exert cytotoxic killing effects." (PMID 35729189, 2022). "In a model for chemically-induced fibrosarcomas, IL-5 overexpression protected mice from tumor establishment through an increased recruitment of eosinophils to the tumor and surrounding connective tissue." (PMID 36032129, 2022). "Upregulation of IL-4, IL-5, and IL-6 was detected in the healthy hemisphere in the first days after tumor resection, which later reverted to basal level, indicating a transient in-brain inflammatory response to the surgical intervention." (PMID 35884700, 2022). "Th1 cytokines, such as IL‐1β, IL‐2, IL‐12, IL‐18, TNFα, and IFNγ, are associated with proinflammation, while Th2 cytokines, such as IL‐4, IL‐5, and TGFβ, play a suppressive role in the tumour immune microenvironment." (PMID 35430766, 2022). "In contrast, Th2 cells secrete anti-inflammatory factors such as IL-4, IL-5, and IL-10 to weaken the anti-tumor immune response." (PMID 35646059, 2022). "For certain genes (Il10, Csf3, Cxcl1, Ccl2, Gata3, Il5, and Il13), there was a clear difference between the EC and HC Shb KO effects using Cdh5-CreERt2 or Vav1-Cre tumor-bearing mice, indicating that these effects reflect EC cell autonomy of Shb gene deletion." (PMID 34768912, 2021). "In cases where it is triggered by neoplasms, IL-5, a growth factor selective for the eosinophil lineage, as well as various cytokines such as IL-3 and GM-CSF, are produced by the tumors." (PMID 34741855, 2021). "While IL-13 signalling in CRC and other tumour types has been associated with a poor prognosis, the role and function of ILC2-derived IL-5 are still poorly understood." (PMID 33535624, 2021). "We found that serum IL-5 and IFN-γ levels were closely associated with tumor burden in metastatic NSCLC and GC patients receiving anti-PD-1 mAbs, so their expression levels can assess the efficacy of anti-PD-1 mAb treatment." (PMID 34239620, 2021). "IL-5 was significantly decreased in the tumours of the EE group compared to the SE group, IL-4 also showed a decreasing trend." (PMID 35008220, 2021). "Eosinophils were shown to protect against tumor development via IL-5 and GM-CSF driving their migration to the tumor and promoting antitumor Th1 cell responses." (PMID 35008550, 2021). "When tumor lesions increased evaluated by imaging methods, serum IL-5 and IFN-γ levels were lower than baseline level." (PMID 34239620, 2021). "Studies have shown that tumour-derived IL-4, IL-5, IL-6, IL-10, and IL-13 can stimulate TAM polarization towards TAM-M2." (PMID 34141479, 2021). "Splenocytes from mRIPO-treated animals provoked varied tumor-specific lymphocyte states as evidenced by expanded baseline and antigen-specific Th1- (IFNγ, TNF), Th2- (IL-5), and Th9- (IL-9) associated cytokine secretion." (PMID 33767151, 2021). "GRO and MCP2 and 3 are known to transform stroma, whereas IL-5 has been shown to modulate tumour environment." (PMID 33758075, 2021).
tumor (continued). "In mouse models of metastatic melanoma, an anti-tumor activity of ILC2s activated by IL-33 has been shown; in this case, ILC2 cells release IL-5, which in turn recruits eosinophils exerting an anti-tumor activity, as also described in CRC." (PMID 34680190, 2021). "The protection against the development of CRC was thought to be mediated by eosinophils that depend on IL-5 and GM-CSF to drive migration to the tumour microenvironment, which in turn, promotes Th1 cell responses against tumours." (PMID 33535624, 2021). "Conversely, exogenous IL-5 treatment resulted in suppressed tumor metastasis and augmented eosinophil infiltration." (PMID 34239620, 2021). "In that study, we observed an increased Th2 response, which is compatible with the finding of increased Il5 expression in CD45+ tumor cells in HC Shb KO mice." (PMID 34768912, 2021). "In vivo studies on ILC2s-driven eosinophils in cancer indicate that ILC2-produced IL-5 promotes blood and tissue eosinophilia that positively correlates with reduced tumor growth." (PMID 33233582, 2020). "The effect of IL-5 on Prevotella is estimated to be positive and equal to 0.64 (posterior mean) and 0.86 for tumor and mucosa tissues, respectively." (PMID 33488574, 2020). "IL-5 also stimulates growth and differentiation of B-cells, and can prime mast cells by increasing their production of pro-tumor and pro-fibrotic cytokines including TNF-α, IL-5, IL-13, MIP-1α, and granulocyte- macrophage colony-stimulating factor (GM-CSF)." (PMID 32552827, 2020). "Compared to the control group, the content of anti-tumor immunity-related cytokines IFN-γ, TNF-a, IL-2, and IL-5 increased, while IL-6, related to inhibiting anti-tumor immunity, decreased in the TME." (PMID 32802195, 2020). "We evaluated the plasma concentrations of Th1 (IL-2, IFN-γ, and TNF-α), Th2 (IL-4, IL-5, IL-6, and IL-10), Th9 (IL-9), and Th17 (IL-17A, IL-17F, IL-21, and IL-22) cytokines in tumor-bearing mice by flow cytometry." (PMID 32802733, 2020). "On the contrary, CD4+ TH2, producing IL-4, IL-5, and IL-13, generally promote tumor growth and development." (PMID 32235370, 2020). "In this study, in the orthotopic-mice model of HCC, YPF increased the levels of Th1 cytokines (IL-2, IL-12, TNF-α, and IFN-γ), decreased the levels of Th2 cytokines (IL-4, IL-5, IL-10, and IL-13), and increased the Th1/Th2 ratio in tumor and adjacent tissues." (PMID 32351590, 2020). "The expression of Th1 cytokines (IL-2, TNF, IFN-γ) and Th2 cytokines (IL-4, IL-5, IL-6, IL-10) were examined in frozen tumor tissues from 80 GC patients by ELISA." (PMID 31417548, 2019). "SKILs were tested for their capacity to produce T helper 1 (Th1) cell cytokines (IFN-γ and IL-2) or T helper 2 (Th2) cell cytokines (IL-5 and IL-10) upon co-culture with the tumor antigen peptides." (PMID 31727154, 2019). "IL-5 recruited eosinophils, leading to an elevated and prolonged lung eosinophilia anti-tumor activity." (PMID 31024531, 2019). "Calcitriol or its analogues downregulated the expression of 4 genes related to the Th1 response in tumour tissue (Ifng (only calcitriol), Socs1, Tbx21 and Fasl) and upregulated 5 genes related to the Th2 response (Ccl11, Ptgdr2, Il9, Asb2 and Il5)." (PMID 31595196, 2019). "Analysis of Siglec-F+PKH26+ cells over the total of PKH26+ tumor cells revealed that IL-33 EO formed increased numbers of cell conjugates with tumor cells, as compared to IL-5 EO." (PMID 31717819, 2019). "Studies have found that healthy mice caged with tumor-bearing mice displayed elevated serum NE levels that correlated with increased production of pro-inflammatory cytokines (IL-4, IL-5) and increased lung inflammation." (PMID 31737559, 2019). "B) Numbers of 4T1 tumor cells in the lungs of 4T1 tumor-bearing mice treated with anti-IL5 antibody or isotype control." (PMID 31488209, 2019).
tumor (continued). "CD4+CD8αα and CD4+CD8αβ T cell clones were then stimulated for 48 h with anti-CD3/CD28 antibodies and supernatants were harvested to measure levels of antitumor Th1-type cytokines (IFN-γ, TNF-α), as well as of pro-tumor Th2-type cytokines (IL-4, IL-5)." (PMID 30984190, 2019). "Conversely, ILC2-produced IL-5 promotes blood and tissue eosinophilia that correlates with reduced tumorigenicity and tumor progression in mice." (PMID 31849977, 2019). "CD11b/CD18 and, to a minor extent, ICAM-1 significantly polarized to the IL-33 EO-tumor cell synapses, whereas they were expressed evenly on the cell membrane of IL-5 EO conjugated with target tumor cells." (PMID 31717819, 2019). "Innate IL-5-producing cells were increased in response to tumor invasion, and their regulation of eosinophils is critical to halt tumor metastasis." (PMID 30483263, 2018). "Regarding tumor surveillance, the majority of neoplasms that have developed during clinical trials with anti-IL-5 are those that are most common in the general population (e.g., basal cell carcinoma, prostate cancer, and squamous cell carcinoma)." (PMID 29682504, 2018). "Decreased expression of IL-5, an important regulator of microglia and infiltrating macrophages in the brain, was also identified in tumor-bearing mice and tumor-free mice receiving radiotherapy alone." (PMID 27893434, 2017). "More specifically, tumor-specific T cell response to tumor-associated antigens MAGE-6 and EphA2 is characterized by a predominance of T cells synthesizing IL5 and IL4, together with reduced levels or a complete absence of T lymphocytes expressing IFNγ." (PMID 28409322, 2017). "Patient 3, who demonstrated a strong (>3000 pg) pre-existing IFN-γ response, developed a strong (>2000 pg) tumor-specific IL-5 response." (PMID 29258618, 2017). "Autologous tumor-specific immune response was seen in two of the three, manifested by IL-5 (1 patient after 3 doses), and IFN-γ, TNF-α, IL-5, IL-10 (after 4 doses in one patient)." (PMID 29258618, 2017). "The tumor localization, from prostate to H&N, showed its effect on the repeatability of the treatment more clearly in dMLC and sMLC_IL5‐based IMRT plans." (PMID 27074451, 2016). "Although ETV6-ACSL6 neoplasms usually lack IL-5 overexpression, there is potential for response to Mepolizumab even when IL-5 is at physiologic levels." (PMID 27746819, 2016). "Pro-inflammatory cytokines such as IL-5, IL-6 and IL-17 are capable of promoting tumour growth which were reduced significantly by Fe-bLf-Dox." (PMID 27576789, 2016). "Since AD is associated with allergen sensitization, elevated serum IgE and increased expression of Type 2 cytokines (IL-4, IL5, and IL-13) in both unaffected skin and skin lesions of AD, candidate gene studies for AD have also focused on the Th2 pathway." (PMID 27777593, 2016). "It is not fully understood what mechanisms drive eosinophil recruitment to the tumor site, although some tumor cells secrete IL-5 and IL-3 that modulate the differentiation and maturation of eosinophils and mast cells." (PMID 25759690, 2015). "CD4+ Th2 lymphocytes elicit anti-tumor activity by releasing IL-5 and activation of eosinophils with tumoricidal properties." (PMID 25801067, 2015). "Numerous mechanisms have been postulated and bone marrow stimulation by cytokines secreted by tumor tissues, including granulocyte macrophage-colony stimulating factor (GM-CSF), G-CSF, IL-3 and IL-5, is most commonly reported." (PMID 23420572, 2013). "In an attempt to potentiate eosinophil survival and function and potentially decrease tumor growth, we added IL-2 (100 ng/ml), IL5 or a combination to the culture media." (PMID 23369060, 2013). "In our case, the immunoreactivity of tumor cells to IL-5 is consistent with that reported in these previous studies." (PMID 23420572, 2013).